INS (insulin)
Diseases named in the same sentence as INS in open-access papers (continued):
Sharing a sentence is not in itself a finding about the gene and the disease.
Obesity (continued). "We have shown previously that maternal obesity programmes epididymal fat of young male mice offspring to overexpress miR-126-3p, resulting in impairment of the insulin signalling pathway via direct downregulation of IRS-1 protein levels." (PMID 33501603, 2021). "Lastly, the NOS3 enzyme has been identified to play an essential role in lipolysis modulation, and obesity condition per se has profound effects on covalent modification of the NOS enzyme by insulin-dependent activation of protein kinase B." (PMID 33924357, 2021). "We sought to determine putative relationships among improved mitochondrial respiration, insulin sensitivity and altered skeletal muscle lipids and metabolite signature in response to combined aerobic and resistance training in women with obesity." (PMID 33770195, 2021). "We suspected that Gpnmb is only secondarily affecting insulin and glucose metabolism in obesity via adipose tissue inflammation." (PMID 34608215, 2021). "Managing obesity is recommended in all obese or overweight diabetic patients as it can improve further glycemic control by improving insulin resistance." (PMID 33802865, 2021). "Accordingly, the role for dietary plasma BCAA reduction as a nutritional strategy to improve metabolic health should be explored in future studies, and take into account obesity, insulin sensitivity, ethnicity, and prevailing levels of circulating BCAAs." (PMID 33996878, 2021). "On the other hand, IUGR is characterized by a transient prenatal downregulation of insulin- and leptin signaling, followed by a postnatal upregulation during catch-up growth resulting in the same pathology as obesity." (PMID 34211985, 2021). "Considering the beneficial effects of BAT on body fatness, insulin sensitivity, macronutrient metabolism and cardiovascular functions, the present results may explain, at least in part, the apparent association of meal timing with obesity and related metabolic disorders." (PMID 34341470, 2021). "These secondary metabolites reduce obesity through modulation of different hormones such as leptin, ghrelin and insulin." (PMID 34071722, 2021). "Decreased circulating TC and TG and elevated glucose levels in women with overweight and obesity seem contradictory if insulin action were mediating this effect." (PMID 34824195, 2021). "Recently, we demonstrated that a dysregulated mitochondrial stress response (MSR) with reduced chaperone expression in the hypothalamus is an early event in obesity development due to insufficient insulin signaling." (PMID 33946318, 2021). "Obesity is significantly closely associated with T2DM, which is characterized by a decreased response to insulin signaling in several types of peripheral tissues, including adipose, liver, and muscle." (PMID 33705353, 2021). "In mice with T2DM and obesity it improved glucose tolerance, reduced fasted insulin level and insulin sensitivity, decreased total body and interscapular fat mass and also increased the activity of interscapular brown fat." (PMID 34959419, 2021). "In obesity, accumulation of lipid droplets in skeletal muscle fibers and a shift towards fast muscle fiber types can both contribute to insulin resistance." (PMID 34082690, 2021). "In consistent to ameliorated lipid accumulation and lipotoxicity, enhanced FAO via LCA promoted insulin-stimulated glucose uptake, thus restored random blood glucose in obesity." (PMID 34899326, 2021). "TNF-α and IL-1β play key roles in the obesity, T2D, and metabolic disorders, disrupting the insulin and lipid signaling pathways, thereby influencing insulin sensitivity and lipid metabolism." (PMID 34712684, 2021). "In subjects with obesity, elevated endogenous opiates can influence the insulin response to glucose through impaired or standard oral glucose tolerance tests." (PMID 34099024, 2021). "In the liver, it enhances high fat diet-induced insulin sensitivity and diminishes obesity, blocking lipogenesis." (PMID 33670130, 2021).
Obesity (continued). "Obesity and myeloma share signaling pathways that upregulate insulin, IGF-1, leptin, and inflammatory cytokines, raising the risk of malignant transformation." (PMID 33531904, 2021). "Obesity correlates with elevated insulin levels, free IGFs, and adipocyte-derived factors, including leptin, the tumor necrosis factor-alpha (TNF-α), and interleukin-6 (IL-6)." (PMID 34298805, 2021). "In recent years, we found key molecular drivers on treatments were targeted NAFLD, including regulating carbohydrate-responsive element-binding protein (ChREBP) to inhibit obesity and insulin-resistant ob/ob mice to reverse hepatic steatosis." (PMID 34884968, 2021). "We found in this long-term study that patients with high FPG and insulin requirement during pregnancy are at an increased risk of developing T2DM, while pregestational obesity is predictive of progression to MetS." (PMID 33021758, 2021). "Disrupted insulin signaling in the brain and the hypothalamic–pituitary–adrenal axis has been proposed as one explanation for the comorbidity of mood disorders and obesity." (PMID 34535768, 2021). "Most studies in mouse models suggest that the ATX-LPA-LPA receptor axis contributes to the obesity-related impairment of glucose homeostasis, insulin resistance, inflammation, mitochondrial dysfunction, tissue fibrosis, hepatic steatosis, and cardiomyopathy." (PMID 34502491, 2021). "ANGPTL6 is highly expressed in obesity, augmented lipid accumulation in skeletal muscle and liver, reduced energy expenditure, and increased insulin resistance." (PMID 33807959, 2021). "The liver plays a key role in preserving glucose homeostasis, contributing to maintain the insulin sensitivity, also during obesity." (PMID 34208379, 2021). "When we increased the simvastatin concentration, the statin normalized palmitate-induced insulin hypersecretion, which has been suggested as a treatment strategy for early obesity intervention." (PMID 34564389, 2021). "and we subsequently validated its utility in predicting the likelihood of NAFLD in healthy controls and insulin-resistant individuals with obesity using proton magnetic resonance spectroscopy (1H-MRS)." (PMID 34309471, 2021). "•Different probiotic strains have been shown to have different beneficial anti-obesity effects such as reduced body weight gain, improvements in insulin sensitivity and glucose uptake, and reduced fat depots accumulation in rodents." (PMID 33349590, 2021). "More recently, administration of A. muciniphila has been shown to improve insulin sensitivity in adults with obesity and IR." (PMID 33596993, 2021). "In line with that, fetuin-A KO mice exhibit improved insulin signaling, and patients with obesity and NAFLD are characterized by high levels of circulating fetuin-A." (PMID 34440850, 2021). "Insulin promotes glucose uptake in the adipose tissue as well as skeletal muscle, which inevitably leads to obesity." (PMID 34417555, 2021). "A recent study reported that long-term AMPK activation has adverse metabolic consequences, such as hyperphagia, obesity, and impaired insulin secretion, eliciting a caution for identifying AMPK activators." (PMID 34671010, 2021). "Insulin has been shown to play an anorexigenic role in the brain and brain imaging studies have revealed a reduced neural response in patients with obesity upon exogenous insulin administration." (PMID 33776816, 2021). "East Asians, including the Japanese, have weak insulin secretory capacity, and lifestyle changes have led to an increase in the number of people with visceral fat-accumulating obesity." (PMID 34203155, 2021). "Insulin-resistant states such as obesity, type 2 DM, metabolic syndrome, and chronic pancreatitis are characterized by higher activity of D6D and lower activity of D5D." (PMID 34822432, 2021). "Studies have shown that the IP6K1-deleted mice phenotype shows enhanced Akt activity, sustained insulin sensitivity, and resistance to obesity as compared to its wild type." (PMID 34445300, 2021).
Obesity (continued). "PA was found to have a positive effect on all obesity-related indicators (e.g., BMI, WC, and %BF), HDL-C, and TG, whereas there was a null association with BP, glucose, and insulin." (PMID 34200736, 2021). "Endothelial cell (EC)-specific Mir181a2b2 KO blocks methotrexate (MTX)-mediated insulin sensitivity and visceral fat inflammation in diet-induced obesity." (PMID 33416495, 2021). "As CR improves insulin secretion capacity in rats with obesity induced by intake of a high-fat diet, it is possible that CR prevents the reduction of blood insulin concentrations." (PMID 33916828, 2021). "It is often accompanied by various metabolic disorders such as obesity, insulin resistances, and others." (PMID 34721298, 2021). "Obesity and consumption of high-fat diet lead to ectopic accumulation of bioactive lipids in insulin-sensitive tissues." (PMID 33815291, 2021). "Obesity produces a marginal increase in the levels of the C-reactive protein and inflammatory factors that disturbs the insulin sensitivity in diverse organs, such as the pancreas, liver, heart, brain, and tissues like the adipose tissue and skeletal muscle." (PMID 34829598, 2021). "Circulating FGF21 levels are elevated in diabetic and obese subjects and administration of FGF21 has been shown to enhance insulin sensitivity and reverses obesity by increasing energy expenditure." (PMID 34680216, 2021). "Paradoxically mice overexpressing GPR43, specifically in adipose tissue, are also protected against diet-induced obesity by suppressing insulin signaling and increasing the consumption of lipids." (PMID 34943862, 2021). "When factors contained in the MetS-WC definition (‘non-metabolic factors’) were removed, the use of glucose-lowering treatment (metformin and insulin) during pregnancy also predicted obesity." (PMID 34750153, 2021). "Live A. muciniphila administration has reversed obesity and metabolism by reducing adiposity, inflammation signs, insulin tolerance, and strengthening gut barrier in HFD mice." (PMID 33802777, 2021). "When including mothers with obesity who received insulin during pregnancy to treat GDM, insulin treatment increased placental PL RNA and protein levels, meeting and exceeding the levels detected in the otherwise healthy lean group of women." (PMID 33743677, 2021). "We also evaluated the effect of insulin in augmenting obesity-driven Py230 tumor growth by implanting insulin pumps in HFD-fed mice." (PMID 33495474, 2021). "Conversely, many studies confirmed that PTP1B downregulation or inhibition improves insulin sensitivity, normalizes blood glucose levels, and protects from obesity and the onset of T2D." (PMID 34443409, 2021). "This leads to altered cell signaling in response to insulin or to other stimuli in obesity and T2DM." (PMID 34440850, 2021). "Another strain with a C57BL/6N background shows late-onset obesity but intact insulin sensitivity at an old age46." (PMID 34873153, 2021). "The relationship between obesity and insulin concentrations has been documented, as a feature of the pathophysiology of T2D." (PMID 34093831, 2021). "Meanwhile, a recent study in individuals with obesity, NAFLD and T2D reported that exercise‐induced changes in peripheral insulin sensitivity were associated with changes in glucose oxidation rather than non‐oxidative glucose disposal rates." (PMID 34042297, 2021). "Taken together, these findings highlight a novel role of adipose tissue macrophages in modulating β cell adaptive proliferation and insulin secretion dysfunction in obesity." (PMID 34572101, 2021). "This short-term meal-associated endocrine regulation of energy balance is disrupted in obesity by development of resistance of peripheral tissues to both insulin and leptin." (PMID 34836068, 2021). "Here, our objective was to characterize the effects of WSD and obesity, alone and together, on maternal glucose tolerance and insulin levels in dams during each pregnancy." (PMID 34155315, 2021).
Obesity (continued). "In this study, the carriers of rs2943640 A allele had significantly higher levels of plasma insulin and HOMA-IR in the groups of patients with T2DM+obesity+CP vs. patients with only T2DM, and also in patients with T2DM+obesity vs. patients with only T2DM." (PMID 35221617, 2021). "At 12 weeks of age, ob/ob (OB) mice presented a marked obesity, hyperglycemia, liver steatosis, and altered insulin-induced AKT phosphorylation in Gast, compared to wild type (WT) littermates." (PMID 34732797, 2021). "The microbe most influenced by this process was Bacteroides acidifaciens, whose growth was previously reported to prevent obesity and improve insulin sensitivity in mice." (PMID 34225711, 2021). "The aim was to verify the effect of non-periodized and linear periodized combined (aerobic plus resistance) exercise training on insulin resistance markers in adults with obesity." (PMID 34568974, 2021). "Hyperinsulinemia, resulting fromeither hypersecretion or reduced insulin clearance, is a symptom of obesity and canlead to IR sensitivity." (PMID 34879109, 2021). "Protein signaling in skeletal muscle provides insight as to mechanisms for improvements in insulin sensitivity in aging and obesity." (PMID 34943997, 2021). "Evidence supports both the roles of energy balance and refined carbohydrates-insulin mechanisms in obesity, with their relative roles likely varying based on genetics and other factors." (PMID 35118102, 2021). "On the other hand, in 12- to 16-year-olds, the significantly higher insulin levels observed in males and females with obesity remain significantly higher after adjusting by leptin." (PMID 35071145, 2021). "Obesity favors systemic endotoxemia (LPS levels) and systemic inflammation shapes glucose and insulin metabolism." (PMID 34302121, 2021). "GLP-1 exerts anti-obesity effects by delaying gastric emptying, reducing food intake, stimulating insulin release, improving insulin sensitivity, and sending appetite suppressor signals through the sympathetic nervous system." (PMID 34512356, 2021). "In obesity, there is an expansion of fat tissue and increased release of pro-inflammatory mediators, including IL-1β, which have been proposed to impair insulin action." (PMID 34638553, 2021). "Authors determined the correlation between iFGF23 serum levels and body composition, blood pressure and selected parameters of glucose, and insulin and fat metabolism in a group of 68 adolescents (mean age 13.9 years) with simple obesity." (PMID 34208131, 2021). "INS was also one of the genes deregulated, displaying upregulation in obesity but downregulation in T2D, confirming previous scRNA-Seq findings." (PMID 33996792, 2021). "Relevant concomitant medications included insulin (100%), statins (19%), angiotensin converting enzyme inhibitors (5%) and the anti‐obesity agent phenmetrazine hydrochloride (5%)." (PMID 33855218, 2021). "Possible pathways for CHMs to alleviate obesity conditions are hunger suppression, metabolic regulation, insulin sensitivity enhancement, and energy expenditure modulation." (PMID 33763238, 2021). "Complementing these findings, adipocyte-specific knockout of KLK7 also prevented obesity-induced inflammation, preserved insulin sensitivity and reduced weight gain in obese mice." (PMID 33866927, 2021). "Adolescence, characterized by changes in body composition, physical fitness, and decreased insulin sensitivity during puberty, is a critical period for preventing the onset and continuation of obesity throughout the lifespan." (PMID 34837002, 2021). "In general, a diet-induced maternal obesity induced obesity, altered brain appetite, insulin and leptin resistance, hypertensive disorders, reduced pancreatic beta-cell function, hepatic steatosis, and nonalcoholic fatty liver disease in the offspring." (PMID 33572203, 2021).
Obesity (continued). "It has been reported that the inhibition of hypothalamic inflammation leads to a reduction in obesity-induced fasting hyperglycemia derived from abnormal gluconeogenesis and insulin resistance in the liver." (PMID 34764855, 2021). "This article will summarize the latest studies on the functions and mechanisms of obesity in BC, including the disorders of adipokines, insulin, and insulin-like growth factor (IGF), endogenous sex hormones, chronic inflammation." (PMID 34350120, 2021). "To fill the gap and create a pioneer study, we aimed to verify the effect of non-periodized and linear periodized combined exercise training on insulin resistance markers in adults with obesity." (PMID 34568974, 2021). "Sprague–Dawley rats fed with a high-fructose diet during 8 weeks showed some metabolic disturbances similar to what is described in human obesity, e.g., ectopic lipid deposition, altered hepatic insulin sensitivity, and increased de novo lipogenesis." (PMID 34630614, 2021). "Obesity-related ectopic fat deposition, especially in the liver, a key insulin-sensitive organ, triggers changes in insulin signaling pathways and insulin resistance." (PMID 34373739, 2021). "LMO3 expression in visceral adipose tissue regulates multiple genes that preserve adipose tissue functionality during obesity, such as glucose metabolism, insulin sensitivity, mitochondrial function, and adiponectin secretion." (PMID 34018016, 2021). "The microvascular vasodilatory response is reduced in obesity, directly contributing to systemic insulin resistance." (PMID 34192532, 2021). "In obesity, high circulating levels of insulin result in upregulation of insulin receptor expression and associated changes in intracellular signaling pathways which together produce impaired insulin sensitivity in adipose, liver, and muscle." (PMID 33777773, 2021). "Metabolic homoeostasis of adipose tissue helps maintain normal blood glucose levels, glucose tolerance, and insulin sensitivity, while chronic inflammation in adipose tissue leads to adipocyte hypertrophy and obesity-related IR." (PMID 33472506, 2021). "Subsequently, the offspring metabolic health trajectory will be evaluated through discussions of obesity, insulin sensitivity, and pancreatic beta-cell mass and function." (PMID 34828683, 2021). "PVA and alginate nanofibers can modulate obesity, reduce blood glucose levels, and reduce serum levels of insulin, ALT, ALP, GGT, creatinine, TNF-α, and IL-1β in diabetic rats." (PMID 34083930, 2021). "GLP-1 affects obesity by delaying gastric emptying decreasing food intake, and modulates glucose homeostasis by stimulating insulin secretion." (PMID 34393826, 2021). "Accordingly, great efforts have been carried out to explore the role of IGFBP2 in obesity state and insulin-related diseases, which it is typically found decreased." (PMID 33498859, 2021). "We found that Zfp217+/− mice were comparable to Zfp217+/+ mice on a normal chow diet, but Zfp217+/− mice were resistant to high-fat diet-induced obesity and were insulin resistant with improved glucose hemostasis." (PMID 34065474, 2021). "Other obesity-induced inflammatory factors include resistin and retinol-binding protein 4, which inhibits insulin signaling and contributes to insulin resistance, respectively." (PMID 33803020, 2021). "Then, to confirm that obesity-induced IR model was successfully established, glucose and insulin tolerance tests were performed." (PMID 33781239, 2021). "Several phytochemicals extracted from leaves and fruits of different members belonging to the Moraceae family showed anti-obesity and anti-diabetic activity, enhancing insulin signaling pathway, glucose uptake, and inhibiting hepatic gluconeogenesis." (PMID 34443409, 2021). "No significant change was observed in substrate oxidation at rest and insulin sensitivity for individuals living with obesity." (PMID 34110721, 2021).